GALC (galactosylceramidase)
Diseases named in the same sentence as GALC in open-access papers (continued):
Sharing a sentence is not in itself a finding about the gene and the disease.
Krabbe disease (continued). "We performed nonclinical studies supporting an investigational new drug (IND) application for the treatment of infantile Krabbe disease using an AAVhu68 vector expressing a codon-optimized GALC administered into the cisterna magna (NCT04771416)." (PMID 35333110, 2022). "This study uses a novel neuron-specific knockout model in the first in vivo attempt to investigate the role of neuronal GALC in neuronal function and the etiology of Krabbe disease." (PMID 35789331, 2022). "GalSph is a substrate of galactocerebrosidase (GALC) and is believed to be the pathological sphingolipid involved in Krabbe’s disease (KD)." (PMID 33971917, 2021). "Krabbe disease is an autosomal recessive, lysosomal storage disease caused by mutations in the GALC gene leading to a deficiency of galactosylceramidase." (PMID 35118033, 2021). "Krabbe disease is caused by recessive mutations in the GALC gene, which encodes galactosylceramidase, a lysosomal enzyme that hydrolyzes galactolipids prevalent in myelin of the central and peripheral nervous systems." (PMID 34142127, 2021). "Due to the poor specificity of GALC for the diagnosis of Krabbe disease, second-tier testing services were provided to reduce the false positive rates for disease monitoring." (PMID 34065072, 2021). "Krabbe disease and MLD are caused by deficiencies in the lysosomal enzymes galactosylceramidase (GALC) and arylsulfatase A (ARSA), respectively." (PMID 34262084, 2021). "The twitcher mouse harbors a mutation in the galactosylceramidase gene (GALC), making it a model of human globoid cell leukodystrophy (Krabbe disease), a lethal lysosomal storage disorder." (PMID 32631408, 2020). "For the first 10 years of screening for Krabbe disease, only the measured percent of daily mean GALC activity was used to move a specimen to a second-tier DNA sequence analysis." (PMID 33239591, 2020). "The diagnosis of Krabbe disease can be made by assay of galactosylceramidase activity via white cell enzyme testing." (PMID 30467211, 2019). "We were able to inhibit 73% of GALC enzyme uptake with M6P added to the culture media every 24–48 h, suggesting that the cross-correction of GALC enzyme activity to Krabbe disease cells is via the M6P receptor lysosomal pathway." (PMID 31132746, 2019). "After 7 days (1 passage) and 14 days (2 passages) of trans-well-mediated co-culturing of GALC NSCs with Krabbe disease fibroblasts, GALC enzyme activity was increased 18- and 34-folds, respectively (right)." (PMID 31132746, 2019). "Krabbe disease (MIM 245200) is a rare inherited metabolic, neurodegenerative disease, due to the deficiency of the enzyme GALC." (PMID 31185936, 2019). "Krabbe disease (globoid cell leukodystrophy, KD; OMIM 245200) is an autosomal recessive demyelinating sphingolipidosis caused by a deficiency in the lysosomal enzyme β-galactocerebrosidase (GALC, EC 3.2.1.46)." (PMID 29342918, 2018). "All first-tier NBS for Krabbe disease is based on measurement of the galactocerebrosidase (GALC) enzymatic activity in DBS using MS/MS or fluorimetry with a 96-well plate reader." (PMID 30882045, 2018). "Missense mutations in the lysosomal hydrolase β‐galactocerebrosidase (GALC) account for at least 40% of known cases of Krabbe disease (KD)." (PMID 27638604, 2016). "The overall sequence identity between mouse and human GALC is 83% and all active site residues are fully conserved making conclusions drawn from this work directly relevant to human Krabbe disease." (PMID 26029356, 2015). "In this regard we have developed the hematopoietic stem cell (HSC)-based gene therapy for Krabbe disease, fatal LSD caused by mutations in the galactocerebrosidase (GALC) gene." (PMID 24705162, 2013). "We used gene-targeted array comparative genomic hybridization (CGH) to analyze the GALC gene in individuals with Krabbe disease in whom sequence analysis with 30-kb deletion analysis identified only one mutation." (PMID 22704718, 2012).
Krabbe disease (continued). "First, genetic counselling and molecular testing for Krabbe disease can be offered to individuals with clinical symptoms, low levels of GALC enzyme, or positive newborn screen results." (PMID 22704718, 2012). "It will be important to examine POAG-related phenotypes in the parents or grandparents of Krabbe disease patients, especially those GALC deletion carriers." (PMID 22073273, 2011). "Murine neural stem cells (mNSCs), either naive or genetically modified to express supranormal levels of β-galactocerebrosidase (GALC), were transplanted into the brain of Twitcher mice, a murine model of globoid cell leukodystrophy, a severe sphingolipidosis." (PMID 21809420, 2011). "Subjects with a single GALC mutant allele do not accumulate undegraded substrates and do not develop Krabbe disease." (PMID 40552465, 2025). "The sustained supranormal GALC activity ensures robust substrate clearance of psychosine and galactosylceramide in demyelination-prone regions over the life span, critical for preventing demyelination and neurodegeneration in Krabbe disease models." (PMID 41439962, 2025). "It is therefore possible that, in addition to a specific role for NF155 in Krabbe disease, increased abundance of other lipids and proteins, as seen in the GALC KO, may hinder myelination via increased electrostatic repulsion." (PMID 36996106, 2023). "Krabbe disease (KD) is a genetic disorder caused by the absence of the galactosylceramidase (GALC) functional enzyme." (PMID 36979906, 2023). "Krabbe disease pathology occurs in patients who possess <10% activity of the catalytic enzyme GALC." (PMID 36996106, 2023). "Globoid cell leukodystrophy (GLD), or Krabbe disease, is a neurodegenerative sphingolipidosis caused by genetic deficiency of lysosomal β-galactosylceramidase (GALC), characterized by neuroinflammation and demyelination of the central (CNS) and peripheral nervous system." (PMID 36012705, 2022). "Krabbe disease (or globoid cell leukodystrophy; OMIM #245200) is an autosomal recessive neurodegenerative disorder that results from deficiency of the lysosomal enzyme galactosylceramidase." (PMID 35308211, 2022). "Globoid cell leukodystrophy, or Krabbe disease (KD), is another autosomal recessive, neurodegenerative disease that is characterized by a defective galactosylceramide β-galactosidase (GALC)." (PMID 33941173, 2021). "The Mayo staff were concerned that screening for Krabbe disease using the conventional method of testing for a single marker (GALC activity) would lead to too many false positive results." (PMID 33239591, 2020). "Psychosine has been shown to be a valuable biomarker when measured in DBS to detect newborns with infantile Krabbe disease, and measuring psychosine as a second-tier test in newborn screening can clarify the vast majority of these low-GALC activity cases as false positives." (PMID 32373753, 2020). "To confirm that GALC cross-correction was mediated through the essential lysosomal mannose-6-phopshate (M6P) receptor pathway, we cultured with M6P to antagonize the enzyme uptake in Krabbe disease fibroblasts." (PMID 31132746, 2019). "Similarly, while all individuals with Krabbe disease have very low GALC enzyme activity (0–5% of physiological levels), there is a relatively broad range of GALC activities in the healthy population." (PMID 27025653, 2016). "Globoid-cell Leukodystrophy (GLD; Krabbe’s disease) is a rapidly progressing inherited demyelinating disease caused by a deficiency of the lysosomal enzyme Galactosylceramidase (GALC)." (PMID 23755134, 2014). "Here we present mutation identification statistics for GALC analysis at Emory Genetics Laboratory (EGL); we also identify two novel GALC deletions and describe the only large GALC duplication reported in an individual with Krabbe disease." (PMID 22704718, 2012).
Krabbe disease (continued). "Mutations in the GALC gene (14q31) cause Krabbe disease, and numerous nonsense, missense, small insertion, and small deletion mutations spanning the entire length of the GALC gene have been described." (PMID 22704718, 2012). "Krabbe disease (globoid cell leukodystrophy) is a rare lysosomal storage disorder characterized by severe demyelination, neurodegeneration, and progressive motor and cognitive deterioration that results from dysfunctional activity of galactosylceramidase (GALC)." (PMID 35921286, 2022). "Thus, we prove for the first time that neuronal GALC is essential to maintain and protect neuronal function independently of myelin and may directly contribute to the pathogenesis of Krabbe disease." (PMID 35789331, 2022). "In addition to low GALC activity, there may be a need for another insult to bring on the onset of clinical features in older patients with Krabbe disease." (PMID 34449528, 2021). "Newborn screenings are available for Krabbe disease with measurement of GALC enzymatic activity in DBS and measurement of psychosine in DBS as second-tier test may help to differentiate infantile from late-onset KD variants, as well as from GALC variant and pseudodeficiency carriers." (PMID 33801069, 2021). "Low GALC activity in this screening test may indicate a diagnosis of Krabbe disease." (PMID 34449528, 2021). "Among them, globoid cell leukodystrophy, or Krabbe disease, is a type of LSD that mainly manifests in the central and peripheral nervous systems due to the loss of the enzyme galactosylceramidase (GALC), which causes death of myelin-producing oligodendrocytes and Schwann cells, respectively." (PMID 31132746, 2019). "Vascular alterations in Krabbe disease may be due to the neuroinflammatory status consequent to the accumulation of the toxic GALC substrate β-galactosylsphyngosine (psychosine) in oligodendrocytes together with a direct effect exerted by GALC deficiency on endothelial cells." (PMID 31091708, 2019). "In the case of Krabbe disease, current data shows that the false positive rate would be lower if the biomarker psychosine was measured as a first-tier test compared to measurement of the activity of the relevant enzyme galactocerebrosidase (GALC) (Section 6.4 below)." (PMID 30882045, 2018). "Genetic deficiency in the lysosomal enzymes arylsulfatase A (ARSA) and galactosylceramidase (GALC) causes metachromatic leukodystrophy (MLD) and globoid cell leukodystrophy (GLD or Krabbe disease), respectively." (PMID 27025653, 2016). "Metachromatic leukodystrophy (MLD) and globoid cell leukodystrophy (GLD or Krabbe disease) are severe neurodegenerative lysosomal storage diseases (LSD) caused by arylsulfatase A (ARSA) and galactosylceramidase (GALC) deficiency, respectively." (PMID 27025653, 2016). "KD NBS programs utilize galactocerebrosidase (GaLC) as an initial test, with psychosine (PSY) activity increasingly used as a confirmatory test for predicting onset of Krabbe disease, though with an excessive false positive rate." (PMID 36412587, 2022). "In this study, MS/MS was mainly used to analyze the activity of IDUA, ABG, ASM, GALC, GLA, and GAA, which are reduced in MPS-I, Gaucher disease, Nimann-Pick disease, Krabbe disease, Fabry disease, and Pompe disease, respectively." (PMID 35419325, 2022). "ABG, ASM, GALC, IDUA, and GAA are lysosomal enzymes with reduced activity in Gaucher disease, Nimann-Pick disease, Krabbe disease, MPS-I, and Pompe disease, respectively." (PMID 35419325, 2022). "The State of Illinois initiated newborn screening (NBS) for Krabbe disease (KD; globoid cell leukodystrophy; OMIM 245200) in December 2017 by measuring galactocerebrosidase (GALC; EC 3.2.1.46) activity in dried blood spots (DBSs)." (PMID 34065072, 2021). "Our data confirm that IGF and AGF are the optimal scaffolds for exploiting this charge-mediated stabilization of GALC and that these molecules have great potential for future PCT and ERT for human Krabbe disease." (PMID 26029356, 2015).
Krabbe disease (continued). "Globoid cell leukodystrophy (GLD), or Krabbe disease, is an autosomal recessive lysosomal storage disease (LSD) caused by mutations in the galactocerebrosidase (GALC) gene leading to deficiency of the enzyme β-galactocerebrosidase, a key enzyme in the catabolism of myelin-enriched sphingolipids." (PMID 24463623, 2014). "While measurement of low GALC activity in leukocytes has been the method of choice for rapid diagnosis of Krabbe disease since 1970, it is not perfect, which became clear as more testing was being done." (PMID 34449528, 2021). "In an experimental model for the treatment of Krabbe’s disease, Katona and colleagues showed that the life span was increased in chimeric model mice when wild-type ES cells with a SATAC containing the human GALC gene was microinjected into the model mouse-derived blastocysts." (PMID 25657031, 2015). "Psychosine may be a dead-end pathway and is hydrolyzed into galactose and sphingosine in individuals who have normal GALC activity, but not in individuals who have Krabbe disease." (PMID 34449528, 2021). "Several of the proteins that we found to be differentially expressed/abundant in Fabry CMs or in the extracellular space have known roles in other LSDs (including Gaucher disease, SCARB2/LIMP-2 and GBA; Krabbe disease, GALC; and ceroid lipofuscinosis, CTSF), but had never been implicated in FD." (PMID 31378672, 2019). "Interestingly, there is no consistent correlation between the residual GALC enzyme activity and the age of onset of Krabbe disease, meaning that some individuals with slightly higher GALC activity may still develop the disease." (PMID 41614773, 2025). "Krabbe disease (KD; globular leukodystrophy globoid; OMIM 245200) is a rare autosomal recessive hereditary disease in which there is lack of galactosylceramidase (GALC) enzyme, which hydrolyzes galactosylceramide and galactosylsphingosine (psychosine, PSY)." (PMID 34975718, 2021). "Lack of either ASA, GALC, or ASAH1 results in a fatal lysosomal storage disease designated as metachromatic leukodystrophy (MLD; OMIM 250100), globoid cell leukodystrophy (Krabbe disease; OMIM 245200), and Farber disease (OMIM 228000), respectively." (PMID 34375644, 2021).
lysosomal storage disorder (25 papers, 2012 to 2025). "Globoid-cell leukodystrophy (GLD), or Krabbe disease, is a lysosomal disorder caused by the deficiency of galactosylceramidase (Galc) secondary to biallelic pathogenic variants in the galc gene that result in impaired activity of the enzyme." (PMID 41354323, 2025). "Krabbe disease (KD), or globoid cell leukodystrophy, is a lysosomal storage disorder caused by mutations in the galc gene that result in impaired activity of the lysosomal hydrolase galactosylceramidase (GALC)." (PMID 37588057, 2023). "KD is a lysosome storage disease (LSD) caused by the functional deficiency of galactocerebrosidase (GALC)." (PMID 36362324, 2022). "Globoid Cell Leukodystrophy (GLD) is a lysosomal storage disease (LSD) caused by inherited defects of the β-galactosylceramidase (GALC) gene." (PMID 32850960, 2020). "GALC, which encodes galactocerebrosidase, is the cause of Krabbe disease, a lysosomal storage disorder." (PMID 30618709, 2018). "Mutations in β-A-mannosidase (MANBA) (OMIM: 248510) and galactosylceramidase (GALC) (OMIM: 245200) lead to lysosomal storage disorders with neurological symptoms or myelination problems, and anti-galactosyl ceramide antibodies are specific for MS." (PMID 23730204, 2012).
demyelinating disorder (9 papers, 2012 to 2025). "Galactocerebroside (GalC), a major myelin glycolipid in Schwann cells and oligodendrocytes, was initially implicated in demyelinating disorders based on its association with neuropathy in rabbits." (PMID 41226806, 2025). "Globoid-cell leukodystrophy (GLD; Krabbe’s disease) is a rapidly progressive demyelinating disease caused by the deficiency of the lysosomal enzyme Galactosylceramidase (GALC)." (PMID 24013457, 2012).
leukodystrophy (7 papers, 2018 to 2024). Leukodystrophies are a group of rare, progressive, metabolic, genetic diseases that affect the brain, spinal cord and often the peripheral nerves. "By showing that the neuronal-specific deletion of GALC in neurons leads to neuroinflammation and mild myelin loss, Kreher and colleagues’ findings reinforce the need to further focus on the neuron-glial crosstalk in the context of leukodystrophies." (PMID 35793314, 2022). "This rare leukodystrophy is characterized by the lack of enzyme galactosylceramidase, leading to the accumulation of toxic psychosine in glial cells causing neuroinflammation, extensive demyelination and death." (PMID 34480290, 2021).
sphingolipidosis (7 papers, 2011 to 2023). An inherited metabolic disorder that affects the lysosomal degradation of the spinhgolipids. "KD is a sphingolipidosis due to mutations in the GALC gene encoding the lysosomal enzyme β-galactocerebrosidase (GALC, EC 3.2.1.46) which catabolizes the hydrolysis of galactose from galactocerebroside and galactosylsphingosine (psychosine)." (PMID 32660097, 2020). "We first focused on an estimation of enzymatic activities of lysosomal hydrolases encoded by genes causing the mucopolysaccharidosis (IDUA) and sphingolipidoses (GCase, ASMase, GALC, GLA) and additional glycogen storage disorders (glycogenosis) (GAA) in patients with late-onset SCZ." (PMID 38248833, 2023). "Apart from the novel variants identified in the GLA gene, GM2A gene, and GALC genes, only one known GBA pathogenic variant was detected in Sphingolipidoses-related genes: the p.Leu483Pro in the GBA gene (patient P1)." (PMID 32883051, 2020).
metachromatic leukodystrophy (6 papers, 2016 to 2025). A rare lysosomal storage disorder characterized by intralysosomal accumulation of sulfatides in various tissues, leading to progressive deterioration of motor and neurocognitive function. "The deficiencies of ARSA or GALC result in the occurrence of metachromatic leukodystrophy (MLD) or Krabbe disease, respectively." (PMID 40054667, 2025). "Two LSDs, Krabbe disease, caused by deficiency of β-galactocerebrosidase (GALC), and Metachromatic leukodystrophy (MLD), caused by deficiency of arylsulfatase A (ARSA), belong to the class of leukodystrophies, manifesting with white matter pathology and progressive degeneration of myelin sheaths." (PMID 38163061, 2023).